ROR2 (ROR family WNT receptor 2)
Diseases named in the same sentence as ROR2 in open-access papers (continued):
Sharing a sentence is not in itself a finding about the gene and the disease.
breast carcinoma (continued). "This is consistent with the observation that patients with breast cancers that express ROR2 had a significantly shorter overall survival than those with tumors lacking expression of ROR2." (PMID 28491097, 2017). "Here, we aim to further investigate activation and outcome of Ror2-dependent non-canonical Wnt signaling in breast cancer." (PMID 28695110, 2017). "Wnt5a-induced formation of mammospheres was not caused by an increase in canonical Wnt/β-catenin signaling, but was instead mediated by noncanonical Wnt signaling requiring the receptor tyrosine kinase ROR2 and the activity of the Jun N-terminal kinase, JNK, in mouse breast cancer cells." (PMID 28491097, 2017). "ROR2 is expressed in the majority of breast cancer patients, but not in normal breast tissue, and this expression confers a poorer disease-specific survival for these patients." (PMID 26328272, 2015). "Since not all basal-like breast cancers are characterized by BRCAness, the two model cell lines MCF-7 and SK-BR-3 might recapitulate these distinct features and indicate that ROR2 is not per se associated with genomic instability." (PMID 34911552, 2021). "In addition to its oncogenic roles in cancers, Wnt5a also has been found to inhibit canonical Wnt/β-catenin signaling in a Ror2-dependent manner and has a tumor suppressor role in several cancer types, such as colorectal cancer (CRC), thyroid cancer, and maybe breast cancers as well." (PMID 27895670, 2016). "Based on the observations of active non-canonical WNT signaling in breast cancer tissue, we compared the expression levels of the known four non-canonical WNT co-receptors ROR1, ROR2, PTK7 and RYK in normal and cancerous breast tissue using the TNMplot database." (PMID 34911552, 2021). "Breast cancer patients, including those with TNBC expressing ROR2, experienced a significantly worse prognosis with shorter overall survival compared to those lacking ROR2." (PMID 34359776, 2021). "To investigate activation and outcome of the Ror2-dependent non-canonical Wnt signaling pathway, we overexpressed the Ror2 receptor in MCF-7 and MDA-MB231 breast cancer cells, stimulated the cells with its ligand Wnt5a, and we knocked-down Ror1 in MDA-MB231 cells." (PMID 28695110, 2017). "At the molecular level, the overexpression of the WNT-selective receptor ROR2 upregulates some non-classical WNT ligands, especially WNT11, and ligand-receptor binding regulated various functional proteins, increasing the invasiveness of breast cancer brain metastases." (PMID 40006075, 2025).
Robinow syndrome (30 papers, 2007 to 2025). Robinow syndrome (RS) is a rare genetic syndrome characterized by limb shortening and abnormalities of the head, face and external genitalia. "Like NXN, bi-allelic loss of function mutations in the WNT5A co-receptor ROR2 causes Robinow syndrome, while mutations in the other causative genes are dominant." (PMID 40044116, 2025). "Variants in DVL, together with variants in WNT5a and ROR2, have been associated with Robinow syndrome, a condition associated with skeletal malformations." (PMID 40271154, 2025). "Analysis of Robinow syndrome mutations in the ROR2 cysteine-rich domain (CRD) and Kringle (Kr) domain." (PMID 38780011, 2024). "(D) Structure of the ROR2 CRD-Kr tandem domains showing the location of the Robinow syndrome mutations." (PMID 38780011, 2024). "Genetic studies have shown that Robinow syndrome (RS), a rare skeletal dysplasia, is caused by ROR2 mutation." (PMID 37307827, 2024). "Human mutations in ROR2 can cause Robinow syndrome, as well as Brachydactyly type B1, including autosomal recessive forms resembling our ror2−/− mutant zebrafish." (PMID 37039156, 2023). "Seven children with Robinow syndrome were enrolled in this study (autosomal recessive caused by homozygous mutations in the ROR2 gene on chromosome 9q22, and the autosomal dominant caused by heterozygous mutation in the WNT5A gene on chromosome 3p14)." (PMID 32172608, 2020). "Stop-gained variants towards the beginning of ROR2 are associated with the autosomal recessive Robinow syndrome, while variants towards the end of the gene are associated with autosomal dominant Brachydactyly type B1." (PMID 32912286, 2020). "Molecular genetic analyses in humans have revealed that mutations in ROR2 cause dominant Brachydactyly type B and recessive Robinow Syndrome, with terminal limb malformations as common symptoms." (PMID 31798639, 2019). "A dominant form of RS is caused by mutations in Wnt/PCP components DVL1, DVL3, and WNT-5A, it is therefore believed that the developmental defects seen in Robinow syndrome are caused by a deregulation of Wnt-5a/Ror2/PCP signaling." (PMID 28523267, 2017). "ROR2 mutations have been described in patients with recessive Robinow syndrome 31, 36, which leads to limb shortening, abnormal development of the spinal vertebrae and brachydactyly (shortened digits), as well as craniofacial abnormalities." (PMID 28833807, 2017). "Skeletal dysplasia due to Smad4 deficiency resembles other skeletal dysplasias resulting from mutations in polarity pathways, such as the Ror2/Wnt5a PCP pathway with Robinow syndrome and brachydactyly B2." (PMID 28167493, 2017). "Participant 94 is a 19-month-old male with several microarray findings including a very small 9q22.31 partial duplication (52 kb in size) including the ROR2 gene which encodes a receptor tyrosine kinase when defective causes Robinow syndrome." (PMID 25400949, 2014). "Cystic kidney has also been observed in Robinow syndrome patients with mutations in Ror2, a receptor for Wnt5a." (PMID 25190059, 2014). "Curiously, Prickle1 mutants recapitulate the characteristic features of human Robinow syndrome and phenocopy mouse mutants with Wnt5a or Ror2 gene defects, prompting us to explore an association of Prickle1 with the Wnt pathway." (PMID 25190059, 2014). "Mutations in ROR2 result in autosomal dominant brachydactyly type B and in the autosomal recessive skeletal dysplasia, Robinow syndrome." (PMID 20683987, 2010). "Additionally, it has been reported in humans that ROR2 mutation is responsible for Robinow syndrome and congenital heart disease in around 15% of the patients." (PMID 37749917, 2023). "The mutations of APC may cause Gardner syndrome, besides gene mutations of Ror2, Dvl1, Dvl3 and Wnt5a are associated with Robinow syndrome." (PMID 37194731, 2023). "Mutations of ROR2 could result in human genetic disorders, like Robinow syndrome and brachydactyly type B (BDB)." (PMID 31878941, 2019).
Robinow syndrome (continued). "Moreover, a separate set of mutations in ROR2 causes autosomal recessive Robinow syndrome (RS), which is characterized by diverse malformations including the axial and limb skeleton." (PMID 28523267, 2017). "Furthermore, mutations in either Wnt5a or its receptor Ror2 in humans lead to Robinow syndrome, distinct from that of other PCP gene mutations." (PMID 25190059, 2014). "Autosomal recessive Robinow syndrome is also caused by mutations in the ROR2 gene." (PMID 18554391, 2008). "(B) Quantification of the effects of Robinow syndrome ROR2 mutants in rescuing WNT5A-ROR signaling, as assayed by GFP-Pdzrn3 degradation." (PMID 38780011, 2024). "(C) Western blots showing the sensitivity of WT ROR2 and Robinow syndrome ROR2 mutants to endoglycosidase H (Endo H) and peptide-N-glycosidase F (PNGase F)." (PMID 38780011, 2024). "(A) Western blot showing expression of wildtype (WT) ROR2 and Robinow syndrome ROR2 mutants in the ROR knockout (KO) immortalized mouse embryonic fibroblast (iMEF) reporter cells." (PMID 38780011, 2024). "In humans, mutations in the ROR2 gene have also been described to cause two genetic disorders associated with severe skeletal defects: brachydactyly type B (BDB) and Robinow syndrome, which points to a central role for ROR2 in human embryogenesis as well." (PMID 33445713, 2021). "The Arg442Ter mutation in ROR2 results in a stop codon right before the predicted NMD cutoff and is associated with the recessively inherited Robinow syndrome." (PMID 32912286, 2020). "Mutations in genes from WNT pathways, including ROR2, FZD2, WNT5A, DVL1, and DVL3, have all been found to cause Robinow syndrome in humans." (PMID 30521570, 2018). "The phenotypic similarity and its role in mediating Wnt5a/Ror2 signaling make Prickle1 a likely candidate gene for Robinow syndrome." (PMID 25190059, 2014). "The deletion does not involve the PTCH1 gene, but instead 30 other gene,s including the ROR2 gene (MIM *602337) which causing both brachydactyly type 1 (MIM #113000) and Robinow syndrome (MIM #268310), and the immunologically active SYK gene (MIM *600085)." (PMID 21693067, 2011). "Of these, receptor tyrosine kinase-like orphan receptor 2 (ROR2) and nucleoredoxin (NXN) are linked to autosomal recessive Robinow syndrome, whereas dishevelled genes (DVL1, DVL2 and DVL3), WNT5A and Frizzled2 (FZD2) have autosomal dominant inheritance (autosomal dominant Robinow syndrome)." (PMID 38967226, 2024). "In a mouse model, Ror2 has been shown to play a crucial role at multiple sites during organogenesis, providing a developmental basis for the distinct clinical features and anomalies described for Robinow syndrome." (PMID 33983923, 2021). "Mutations in FZ-CRD of Frizzled class receptor 4 (FZD4) and Muscle, skeletal, receptor tyrosine kinase (MuSK) and Receptor tyrosine kinase-like orphan receptor 2 (ROR2) cause Familial Exudative Vitreoretinopathy (FEVR), Congenital Myasthenic Syndrome (CMS), and Robinow Syndrome (RS) respectively." (PMID 31892318, 2019). "In addition to the bulldog DVL2 frameshift mutation, human mutations causing Robinow syndrome have been identified in WNT5A, ROR2, FZD2, DVL1, and DVL3, which are all major components of the WNT5A-ROR pathway." (PMID 30521570, 2018). "Robinow syndrome can also be caused by mutations in other genes that are important in the WNT/PCP signaling pathway, including WNT5A (OMIM 180700), the disheveled genes DVL1 (OMIM 616331), DVL2, and DVL3 (OMIM 616894), and the WNT co-receptors FZD2 and ROR2 (OMIM 268310)." (PMID 40044116, 2025). "The receptor tyrosine kinase ROR2 mediates noncanonical WNT5A signaling to orchestrate tissue morphogenetic processes, and dysfunction of the pathway causes Robinow syndrome, brachydactyly B, and metastatic diseases." (PMID 38780011, 2024).
Robinow syndrome (continued). "For non-canonical Wnt signaling these include both autosomal dominant and recessive forms of Robinow syndrome (ROR2, WNT5A, DVL1, DVL3, FZD2, NXN), Brachydactyly type B1 (ROR2), Kleipert syndrome and Simpson-Golabi-Behmel syndrome type 1 (GPC4)." (PMID 37039156, 2023). "Accordingly, none of the six previous patients, nor our patients, whose deletion includes ROR2, have either brachydactyly type B1 or features of Robinow Syndrome [3 (restudied in 15),]." (PMID 21693067, 2011). "Analysis of the ROR2 gene performed in 2009 failed to confirm the hypothesis of Robinow syndrome." (PMID 30455931, 2018).
osteosarcoma (25 papers, 2010 to 2025). A usually aggressive malignant bone-forming mesenchymal neoplasm, predominantly affecting adolescents and young adults. "In recent years, the literature has indicated that ROR2 is implicated in various cancers including metastatic melanoma, osteosarcoma, and renal cancer." (PMID 26305508, 2015). "Receptor tyrosine kinase-like orphan receptor 2 (ROR2) has been identified as a highly relevant tumor-associated antigen in a variety of cancer indications of high unmet medical need, including renal cell carcinoma and osteosarcoma, making it an attractive target for targeted cancer therapy." (PMID 30450096, 2018). "In osteosarcoma cells, ROR2 enhances the transcriptional response to Wnt135; in lung carcinoma cells, ROR2 activates Wnt3a-induced canonical Wnt signaling as a co-receptor with Fzd231." (PMID 35915068, 2022). "Similar to ROR1, ROR2 supported proliferation and tumor growth, while inhibiting apoptosis both in vitro as well as in vivo in mouse models of osteosarcoma, breast and renal cancer." (PMID 33445713, 2021). "ROR2 knockdown led to an accumulation of osteosarcoma cells in the G0/G1 phase suggesting that ROR2 itself is essential for cell cycle progression." (PMID 33445713, 2021). "Here, we transfected osteosarcoma MG-63 cells with ROR2-Flag or stable ROR2 knockdown MG-63 cells, then were incubated with 100 ng/mL of Wnt5a and subjected to clonogenic assays." (PMID 29213214, 2017). "Wound healing assays were used to measure the migration rate of osteosarcoma cells transfected with shRNA or siRNA specific against ROR2 or indicated constructs." (PMID 29213214, 2017). "Clonogenic assays were used to measure the cell proliferation of ROR2-knockdown or ROR2-overexpressed osteosarcoma cells." (PMID 29213214, 2017). "Specific inhibitors targeting PI3K and Akt retard Wnt5a-induced cell migration in ROR2-overexpressed osteosarcoma cells." (PMID 29213214, 2017). "Given that PI3Kα/Akt signaling (specific PI3Kα, Akt1 and Akt2 isoforms) mediate Wnt5a-induced the migration of osteosarcoma cells, we propose that PI3Kα/Akt act as the downstream of Wnt5a and ROR2." (PMID 29213214, 2017). "Wnt5a-induced osteosarcoma cell migration was largely abolished by shRNA or siRNA specific against ROR2." (PMID 29213214, 2017). "We present the evidence here that ROR2 mediates Wnt5a-induced osteosarcoma cell migration via PI3K/Akt and RhoA signaling." (PMID 29213214, 2017). "miR-124 inhibited cell growth and invasion in osteosarcoma cells by targeting ROR2, SPHK1, Rac1 and B7-H3." (PMID 29113367, 2017). "To gain new insight into how constitutively activated Ror2 signaling promotes tumor invasiveness, we initially performed a microarray analysis on a human osteosarcoma cell line, SaOS2 (GEO accession number: GSE76535)." (PMID 28127051, 2017). "In this study, overexpression of constitute active RhoA rescues Wnt5a-induced cell migration blocked by shRNA or siRNA against ROR2 in osteosarcoma cells." (PMID 29213214, 2017). "The differing effects of these various contextual spheres is well illustrated in osteosarcoma cells where Ror2-dependent expression of MMP13 has been shown to be mediated through either through Dvl2 and Rac1 in SaOS-2 cells or Dvl3 in U2-OS cells." (PMID 25542006, 2014). "In osteosarcoma cells, suppressed expression of ROR2 (or its extracellular effector, WNT5A) inhibits cell invasiveness and decreases invadopodium formation." (PMID 20591152, 2010). "Interestingly, ROR1 or ROR2 upregulation has been observed in many cancers: ROR1 is upregulated in solid tumors or hematologic malignancies while ROR2 is overexpressed in osteosarcomas or renal cell carcinomas." (PMID 35295854, 2022). "Next, we used constitute activity constructs (RhoA-CA, RhoA-V14) to elevate RhoA activity in osteosarcoma cells and checked whether the reductive migration rate by ROR2 knockdown could be rescued." (PMID 29213214, 2017).
osteosarcoma (continued). "Here, we demonstrate that ROR2 mediates Wnt5a-induced cell migration of osteosarcoma." (PMID 29213214, 2017). "ROR2 is reported to have oncogenic properties in other tumour types such as oral cancer, renal cancer and osteosarcoma; it is frequently overexpressed in these tumours, and its suppression in renal cancer cells inhibits cell migration and growth in orthotopic xenograft models." (PMID 20591152, 2010). "ROR2 is overexpressed in oral and renal cancer, and in osteosarcoma." (PMID 20591152, 2010). "Thus, ROR2 participates in Wnt5a-induced osteosarcoma cell migration." (PMID 29213214, 2017). "Because higher Ror2 expression has a prior mentioned potential to serve as an independent biomarker in osteosarcoma, colorectal cancer, GIST,leiomyosarcoma, and as part of 34 gene panel in ccRCC we sought to determine whether Ror2 expression could serve as an independent prognostic factor in ccRCC." (PMID 25542006, 2014). "Regarding ROR2, it has been reported to interact with WNT5B in osteosarcoma cells and preliminary results from our group indicate that WNT11 acts as a ligand for ROR2." (PMID 33445713, 2021). "In osteosarcoma, it has been identified that the interaction of WNT5B and ROR2 can enhance cell migration, which supports a potential role of ROR2 and WNT5B in the metastatic pathway of osteosarcoma cells." (PMID 34017835, 2021). "In this setting, we have previously shown that the expression of both Wnt5a and Ror2 is dependent, at least in part, on the epithelial-to-mesenchymal transition (EMT)-related transcription factor Snail in human osteosarcoma SaOS2 cells." (PMID 28127051, 2017). "To assess the effect of ROR2 receptors on Wnt5a-induced osteosarcoma cell migration, we generated the stable ROR2 knockdown MG-63 cells and transfected U2OS cells with specific siRNA targeting ROR2 and measured the cell migration by wound healing assays." (PMID 29213214, 2017). "In osteosarcoma where ROR2 acts as an oncogene, downregulation of ROR2 inhibited cell invasiveness through the non-canonical (β-catenin independent) Wnt signalling pathway." (PMID 33494187, 2021). "ROR2 is a receptor tyrosine kinase involved in WNT-5a signaling, has been described as a prognostic biomarker as well as a potential therapeutic target in gastrointestinal stromal tumors and leiomyosarcomas, and its expression correlates with disease severity in osteosarcoma." (PMID 36508875, 2023). "Lastly, Wnt5a/ROR2 signaling does not alter the cell proliferation of MG-63 osteosarcoma cells." (PMID 29213214, 2017). "Neither overexpression nor knockdown of ROR2 did not alter the proliferation of osteosarcoma cells." (PMID 29213214, 2017). "Finally, we find that Wnt5a/ROR2 signaling does not affect the proliferation of osteosarcoma cells." (PMID 29213214, 2017).